CPED1 (cadherin like and PC-esterase domain containing 1)
Synonyms: C7orf58; FLJ21986
Tractability: Antibody: UniProt predicts a signal peptide or a membrane-spanning region.
Gene: Protein-coding gene on chromosome 7 (120,988,697 to 121,297,980, forward strand). Ensembl gene ENSG00000106034.
Subcellular location (Human Protein Atlas): Nucleoplasm
Gene Ontology:
Cellular component: endoplasmic reticulum
Genetic constraint (gnomAD): Loss-of-function variants: 73 observed, 77.69 expected, observed/expected ratio (o/e) 0.94, 90% interval 0.78 to 1.14. The upper end of that interval is the gene's LOEUF score, 1.14, which puts it in group 5 of 6, group 1 being the genes least tolerant of losing a copy. Missense variants: 868 observed, 895.41 expected, observed/expected ratio (o/e) 0.97, 90% interval 0.92 to 1.02. Synonymous variants: 348 observed, 328.43 expected, observed/expected ratio (o/e) 1.06, 90% interval 0.97 to 1.16.
Homologues: Orthologues: chimpanzee CPED1 (99% identical), macaque CPED1 (96% identical), rabbit CPED1 (83% identical), pig CPED1 (82% identical), dog CPED1 (79% identical), guinea pig CPED1 (79% identical), mouse Cped1 (75% identical), rat Cped1 (74% identical), tropical clawed frog cped1 (40% identical), zebrafish cped1 (35% identical).
Diseases named in the same sentence as CPED1 in open-access papers:
CPED1 is named in the same sentence as 17 diseases in open-access papers, as found by Europe PMC text mining. Sharing a sentence is not in itself a finding about the gene and the disease. The quoted sentences say what the papers report.
breast carcinoma (2 papers, 2018 to 2024). "Similar to the analysis of BMP6 expression, the data suggest that Snail1 may regulate CPED1 expression in all subtypes of breast cancers." (PMID 29729076, 2018). "We therefore suggest that CPED1 may represent a gene whose transcriptional repression by Snail1 may be important for a subset of breast cancers." (PMID 29729076, 2018). "We queried the human breast cancer cell collection of the GOBO database and identified 14 cell lines in which high‐level Snail1 correlated with low CPED1, or inversely, low‐level Snail1 correlated with high‐level CPED1." (PMID 29729076, 2018).
osteoporosis (2 papers, 2022 to 2023). A condition of reduced bone mass, with decreased cortical thickness and a decrease in the number and size of the trabeculae of cancellous bone (but normal chemical composition), resulting in increased fracture incidence. "Next, we analysed six selected SNPs in 631 patients evaluated for osteoporosis [rs2707518 (CPED1/WNT16), rs3779381 (WNT16), rs115242848 (LOC101927709/EN1), rs10239787 (JAZF1), rs603424 (PKD2L1) and rs6968704 (JAZF1)]." (PMID 37831088, 2023). "From this list, we selected the five SNPs with the lowest p-values for further analyses in patients evaluated for osteoporosis: rs2707518 (CPED1/WNT16), rs3779381 (WNT16, intron 1), rs115242848 (LOC101927709/EN1), rs10239787 (JAZF1, intron 2), and rs603424 (PKD2L1, intron 2)." (PMID 37831088, 2023).
Duchenne muscular dystrophy (1 paper, 2021). Duchenne muscular dystrophy (DMD) is a neuromuscular disease characterized by rapidly progressive muscle weakness and wasting due to degeneration of skeletal, smooth and cardiac muscle. "Variants near CPED1 and WNT16 have been reported to have pleiotropic effects on LM and BMD in the pediatric population, and it has been reported that in Duchenne Muscular Dystrophy patients, up-regulation of CPED1 by muscle-specific microRNAs improved skeletal muscle function." (PMID 33889153, 2021).
lung adenocarcinoma (1 paper, 2017). A carcinoma that arises from the lung and is characterized by the presence of malignant glandular epithelial cells. "In the GSE10072 array, GNG11 and CPED1 expression is downregulated in lung adenocarcinoma." (PMID 29285217, 2017). "Our data showed that CPED1 may play a role as a potential tumor suppressor in lung adenocarcinoma." (PMID 29285217, 2017). "Survival curve analysis revealed that lung adenocarcinoma patients with high expression of ZDHHC9, BTNL9, GNG11 or CPED1 are correlated with better survival outcomes." (PMID 29285217, 2017). "The analysis of the effects from each gene expression on survival outcome indicated that 6 genes (AGR2, SPDEF, CDKN2A, CLDN3, SFN, and PHLDA2) play oncogenic roles, and 7 genes (PDK4, FMO2, CPED1, GNG11, IL33, BTNL9, and FABP4) act as tumor suppressors in lung adenocarcinoma." (PMID 29285217, 2017). "The mRNA expression of BTNL9, GNG11, or CPED1 is downregulated in lung adenocarcinoma when compared to normal tissue, and ZDHHC9 is upregulated." (PMID 29285217, 2017). "However, since the genetic interactions of hsa-miR-183-5p-BTNL9, hsa-miR-33b-5p-CPED1, hsa-miR-429-CPED1, hsa-miR-182-5p-FMO2, hsa-miR-130b-5p-IL33, and hsa-miR-542-3p-IL33 have not been identified, these altered genetic regulations may play important roles in the progression of lung adenocarcinoma." (PMID 29285217, 2017).
tumor (4 papers, 2017 to 2023). "Five of the seven samples showing the ASE of CPED1 in the normal mucosa also retained the ASE of CPED1 in the paired tumor sample." (PMID 31093489, 2019). "In addition, seven samples showed the ASE of CPED1 in the tumor sample but not in the paired normal mucosa, indicating that these cancers acquired ASE of CPED1 during tumorigenesis." (PMID 31093489, 2019).
cancer (3 papers, 2019 to 2024). A tumor composed of atypical neoplastic, often pleomorphic cells that invade other tissues. "CPED1 showed heterogeneous ASE in both normal mucosa and cancer samples." (PMID 31093489, 2019).
bone disorder (1 paper, 2018). "The biology of CPED1 remains unexplored, and so far, this gene is linked to bone disorders based on genomewide association studies." (PMID 29729076, 2018).
CPED1 also shares sentences with these, for which no sentence is quoted: anxiety disorder (1 paper); Coffin-Siris syndrome (1); mesothelioma (1); metabolic syndrome (1); Potocki-Shaffer syndrome (1); prostate carcinoma (1); prostate tumor (1); prostatic intraepithelial neoplasia (1); stomach adenocarcinoma (1); type 2 diabetes (1).